IFNAR1 (interferon alpha and beta receptor subunit 1)
Diseases named in the same sentence as IFNAR1 in open-access papers (continued):
Sharing a sentence is not in itself a finding about the gene and the disease.
infection (continued). "Notably, sorted infected WT and Ifnar1-/- iMOs had similar levels of infection when measured as viral transcripts by qPCR or as infectious particles/cell by plaque assay." (PMID 34015056, 2021). "In order to investigate whether NK cells were involved in the different outcome of PbA-infection in WT and Ifnar1-/- mice, NK cells were depleted using anti-NK1.1 antibodies." (PMID 34659202, 2021). "Infection with live NoVΔB2 also induced significant inhibition on the accumulation of SINVNoV compared to that of SINVGFP in type I IFN receptor knockout mice (Ifnar1-/-), which are defective in the signaling by type I IFNs." (PMID 34343211, 2021). "Indeed, when we performed a timecourse of bacterial replication in WT and Ifnar1-/- iBMDMs, we saw that the increased bacterial abundance phenotype we’d seen in Ifnar1-/- cells only emerged late in the infection." (PMID 33684179, 2021). "(c) Survival of Ifnar1-/-;Ifngr1-/- mice upon i.d. infection with 107 PFU of R. parkeri." (PMID 34423779, 2021). "I.d. infection of Ifnar1-/-;Ifngr1-/- mice by R. parkeri elicits disseminated, lethal disease." (PMID 34423779, 2021). "Ifnar1-/-;Ifngr1-/- mice were immunized with ompB or sca2 mutant R. parkeri by i.d. infection or with sca2 mutant R. parkeri by i.v infection and rechallenged 40 d later by i.d. infection with 105 WT bacteria." (PMID 34423779, 2021). "DENV2 could be detected in the serum of both KitW-sh/W-sh Ifnar1−/− Ifngr1+/+ and KitW-sh/W-sh Ifnar1−/− Ifngr1−/− mice during acute infection." (PMID 34066286, 2021). "As the RNAseq data showed enrichment of FA metabolism genes in both Irf9-/- and Ifnar1-/- livers during infection, we compared FA levels in more detail by hypothesis testing." (PMID 34237114, 2021). "We observed similar frequencies and infection rates of WT and Ifnar1-/- iMOs, indicating that IFNAR deficiency does not affect iMOs recruitment from the blood to the dLN." (PMID 34015056, 2021). "However, the number of bacteria delivered from tick infestation likely varies depending on many factors, and we therefore sought to examine the effects of different doses of R. parkeri upon i.d. infection of Ifnar1-/-;Ifngr1-/- mice." (PMID 34423779, 2021). "However, in both Irf9-/- and Ifnar1-/- livers the KB acetoacetate and hydroxybutyric acid were decreased three days post-infection." (PMID 34237114, 2021). "In contrast with WT bacteria, i.d. infection of Ifnar1-/-;Ifngr1-/- mice with ompB::TnSTOPR. parkeri caused no lethality or weight loss." (PMID 34423779, 2021). "Further, FCV 2280 infection contributes to degradation of IFNAR1 mRNA." (PMID 33075108, 2020). "Interestingly, in addition to intrinsic differences in cytokine expression in uninfected Ifnar-/- animals, reduced expression of immune cell chemoattractants was observed on day 3 post-infection for Ifnar1-/- mice compared to WT controls during HTNV infection." (PMID 32330200, 2020). "Generally, studies suggesting IFN-I suppression of T cell activation or enhancement of inflammatory chemokines/cytokines used Ifnar1-/- mice or multiple injections of anti-IFNAR antibodies, which are different from infections having a short time increase in IFN-I level." (PMID 33344264, 2020). "Indeed, Ifnar1-/- mice had higher viral load in all tissues examined, with viral RNA in Ifnar1-/- mice present late through infection in contrast to WT controls." (PMID 32330200, 2020). "Both results revealed that IFNAR1 mRNA expression was reduced during FCV 2280 infection." (PMID 33075108, 2020). "Next, we explored whether FCV 2280 infection led to the decrease of interferon receptors IFNAR1 and IFNAR2, which inhibits downstream adaptor activation." (PMID 33075108, 2020). "Therefore, the objectives of the present study were to explore the TPT potential of wild Indian BTV-1 at early and mid stages of gestation after experimental infection in IFNAR1-blocked mice." (PMID 32034180, 2020).
infection (continued). "Additionally, Ifnar1−/− mice inoculated with the X1 mutant virus gained weight during acute infection with an average increase of 3.8% at 6 DPI." (PMID 33080971, 2020). "Moreover, in contrast to the findings described by a study using NS1-based DNA vaccine, our formulations was capable to confer protection in IFNAR1−/− mice even after challenge with a high infection dose (106 PFU)." (PMID 35047887, 2020). "Low levels of IFN-β production in response to infection combined with lower basal levels of IFNAR1 in the newborn lead to impaired type I IFN signaling, resulting in the breakdown of the BBB, rapid spread of HSV-1 to the CNS, and uncontrolled viral replication in the brain parenchyma." (PMID 32457247, 2020). "However, ultimately all of the CD8+ T cell depleted mice succumb to infection where the most of the isotype control treated mice recovered demonstrating that CD8 T cells are necessary for protection against ZIKV mortality in Ifnar1-/- mice." (PMID 31379867, 2019). "Hepatocyte-intrinsic IFNAR1 signaling mainly regulated metabolic genes on day 2 after infection." (PMID 31784108, 2019). "All Ifnar1-/- mice started losing weight at 2 dpi and succumbed to infection at 8 dpi." (PMID 31194854, 2019). "After ECTV infection, Ifnar1-/- mice had significantly higher levels of ECTV gene transcription than B6 controls in the skin of the footpad and in the dLN at 2 dpi whether receiving cGAMP or not." (PMID 31877196, 2019). "Indeed, inoculation of Ifnar1-/- mice with low doses of BRBV-STL resulted in high viral titers in liver and spleen, weight loss, and uniform death 7–10 days after infection." (PMID 31194854, 2019). "Moreover, administration of favipiravir as a prophylaxis or as post-exposure therapy three days after infection prevented BRBV-STL-induced mortality in immunocompromised Ifnar1-/- mice." (PMID 31194854, 2019). "The striking increase in full length pro-caspase 8, as well as active caspase 8, in Ifnar1-/- mice was apparent prior to infection, suggesting Ifnar1-/- mice may be poised to resist RIPK1-dependent cell death." (PMID 30080899, 2018). "In the Ifnar1-/- mice the difference in mortality corresponded to a significant weight loss in CD4 depleted versus control animals and more severe clinical signs of disease during the course of infection." (PMID 30212537, 2018). "WT mice exhibit profound rescue of HSCs and HSPCs upon RIPK1 antagonism with Nec-1s, similar to what is observed in Ifnar1-/--deficient mice, consistent with a central role for RIPK1 kinase activity in the demise of the hematopoietic compartment in IOE infection." (PMID 30080899, 2018). "Importantly, Ifnar1−/− mice shed significantly less virus than Ifnlr1−/− mice at all time points between days 2 and 4 post infection, indicating that IFN-λ is the dominant limiting factor for virus shedding." (PMID 29651984, 2018). "We depleted CD4+T cells from Ifnar1-/- mice prior to infection with ZIKV." (PMID 30212537, 2018). "At this time, both HSPCs (Lineage-, c-Kit+) and phenotypic long-term HSCs (Lineage- c-Kit+ CD135- CD150+ CD48) were depleted from the BM of WT mice during infection, but in Ifnar1-/- mice HSPCs were maintained and HSCs underwent a significant expansion as determined by both frequency and number." (PMID 30080899, 2018). "Infection of Ifnar1-/- mice resulted in a striking increase in phenotypic HSCs." (PMID 30080899, 2018). "However, infection of dorsal root ganglia neurons in Ifnar1 knockout mice in vivo was reported recently." (PMID 30050403, 2018). "We also noted that the more susceptible Ifnar1-/- mice that did not succumb to infection had viral titers persist for greater than 30 days after infection with ZIKV, possibly leading to a more exhausted T cell population." (PMID 30212537, 2018). "In L. amazonensis-infected 129Sv mice, which develop non-healing, progressive skin lesions, deletion of IFNAR1 was associated with a markedly attenuated clinical course of infection and parasite load." (PMID 29459858, 2018).
infection (continued). "Interestingly, the K. pneumoniae-induced type I IFNs have no autocrine functions since mice lacking Ifnar1 in alveolar macrophages, the key sentinel cells in the lung, are similarly resistant to infection as Ifnar1-proficient mice." (PMID 29112952, 2017). "Both Ifnar1-/- and WT mice exhibited similar bacterial burdens 12 h post infection (p.i.)." (PMID 29112952, 2017). "To assess the effects of IFNAR1 signaling on S. typhimurium-induced colonic inflammation, we examined and scored the histopathological condition of the colon and cecum of WT and Ifnar1-/- mice on days 3 and 5 after infection." (PMID 29190678, 2017). "As neither C57BL/6 wild-type nor Ifnar1−/− mice succumbed to the infection during these time frames, the impact of Ifnar1 single deficiency on survival upon infection with these M. tuberculosis strains remained unclear." (PMID 29230217, 2017). "To assess whether there were differences in bacterial colonization that were driving the differential outcome of the disease, we measured bacterial CFU in the feces of WT and Ifnar1-/- mice on day 1 after infection." (PMID 29190678, 2017). "In contrast, expression of other genes in the IFN signaling pathway (G1p2, Ifi35, Ifit1 and Stat2) were shown to be higher in the infected WT as compared to the infected Ifnar1-/- mice after days 2 and 3 of infection, when the bacterial load was lower in the infected Ifnar1-/- mice." (PMID 26918359, 2016). "As hypothesized, the levels of inflammatory mediators (IL-6, CCL2, CCL3, CXCL1, CXCL10 and IFNα as expected) were lower in the blood and the spleen of Ifnar1-/- mice compared to WT counterparts at all times post-infection, except for IFNγ." (PMID 27792766, 2016). "Despite having observed that the induction of Irf9 was greater in the Ifnar1-/- compared to the WT following infection in all three tissues, the final expression values of Irf9 remained lower in the Ifnar1-/- mice following infection than that observed in WT mice even before infection." (PMID 26918359, 2016). "In addition, we show that different changes in the gene expression profile in blood and tissues in Ifnar1-/- as compared to WT mice are observed at varying times post-infection." (PMID 26918359, 2016). "The expression levels of both type I and type II IFN inducible genes following infection as shown by the Molecular Distance to Health (MDTH) was reduced in the Ifnar1-/- compared to the WT mice at day 3 post infection where the bacterial load was much diminished in the infected Ifnar1-/- mice." (PMID 26918359, 2016). "Finally, we observed no substantial differences in the cellularity of the spleen, or bulk CD4+ T cell or B-cell numbers, in WT versus Ifnar1-/- mice during PcAS infection, Py17XNL infection, or in un-infected mice." (PMID 27812214, 2016). "However, its basal level of expression in Ifnar1-/- mice was so low to start with that its final expression in blood and tissue upon infection remained lower than that seen in the WT mice before infection." (PMID 26918359, 2016). "Strikingly, an upregulation of a significant number of those transcripts was observed at day 1 post infection in blood of the Ifnar1-/- as compared to WT mice, whereas the opposite was observed at day 3 post infection where decreased transcriptional expression was observed." (PMID 26918359, 2016). "However, the duration of this effect would require scrutiny, since in our mouse models, antibody levels normalized between Ifnar1-/- and WT mice by the seventh week of infection." (PMID 27812214, 2016). "Next, we found that IFNAR1-signalling impeded the resolution of non-lethal blood-stage infection, which was associated with impaired production of parasite-specific IgM and several IgG sub-classes." (PMID 27812214, 2016).
infection (continued). "In addition we show that genes are not only differentially expressed upon infection but also in the uninfected state in Ifnar1-/- as compared to WT mice, which likely contributes to the net global expression changes, which we observe after infection." (PMID 26918359, 2016). "This lower Stat1 expression may explain in our system the observation of diminished type II IFN inducible gene expression in the Ifnar1-/- compared to the WT following infection." (PMID 26918359, 2016). "Moreover, IFNAR1-mediated regulation of ICOS expression in CD4+ T cells was observed in both the Th1 and emerging Tfh compartments during PcAS infection; and IFNAR1-signalling also reduced ICOS+ Tfh cell numbers during Py17XNL infection." (PMID 27812214, 2016). "Immunohistochemistry revealed heavy infection of IECs in the terminal small intestine and colon of Ifnlr1-/- mice, whereas the virus was largely localized to the lamina propria region of the small intestine in Ifnar1-/- mice." (PMID 25849543, 2015). "Because aggressive recruitment of Gr1 + CD11b + cells was observed after day 3 post-infection, we wondered whether intranasal treatment with an anti-IFNAR1 blocking antibody at day 3 post-infection could interrupt the influx of CCR2+ inflammatory monocytes." (PMID 25407417, 2014). "For some viruses (including influenza virus and RSV), the effect of IFNAR1 deficiency is not as severe and does not impact on survival from infection." (PMID 24648449, 2014). "Interestingly, differences in early cytokine production after i.g. infection of Ifnar1−/− mice were more pronounced in spleen than in the gut epithelium or gut-associated lymphoid tissue." (PMID 23840314, 2013). "The median blood bacterial titer was also increased by anti-IFNAR1 treatment: At 18 hours post-infection, the median bacterial titer was 11-fold higher in anti-IFNAR1-treated animals, a difference which further increased at 24 h and 30 h to 19- and 17-fold, respectively." (PMID 24244159, 2013). "It is interesting to note that while resistance to primary infection with ECTV requires T1-IFN function, resistance to secondary infection does not as IFNAR1 deficient mice immunized with attenuated ECTV or VACV resisted a challenge with WT ECTV." (PMID 22241999, 2012). "To confirm the importance of type I IFN signalling for antiviral responses to RV infection in the mouse model, we performed parallel infection experiments with wild-type (wt) and IFNAR1−/− mice and observed that production of type I and type III IFNs was significantly impaired." (PMID 23165884, 2012). "Since the decrease in cell apoptosis resulting from either Stat1 or Ifnar1 ablation was highly similar, the additional protection of LckCreStat1flfl mice from Lm infection is not due to a lesser rate of infection-induced apoptosis in Stat1-deficient T cells." (PMID 22719255, 2012). "It has been previously shown that WT mice become resistant to CHIKV induced lethality between 9 to 12 days of age, while mice lacking IFNAR1 remain susceptible to infection even as adults." (PMID 22028657, 2011). "A comparable decrease of IFNAR1 levels in response to infection was seen in WT-5 and KR-2 cells." (PMID 21695243, 2011). "Finally, in the isogenic fibrosarcoma U5A, cells that lack the IFNAR2 chain of the Type I IFN receptor and are insensitive to any Type I IFN, infection with HSV robustly induced Ser535 phosphorylation of IFNAR1." (PMID 21695243, 2011). "Consistent with our previous observations in adult mice, neonatal pups lacking IFNAR1 were highly susceptible to CHIKV infection with 100% of the pups dying by day 2 post-infection." (PMID 22028657, 2011). "Therefore, we determined kinetics of IFNβand IRF2 expression during MHV68 infection in the spleen of wildtype, IFNAR1-/-, and IRF2-/- mice." (PMID 22114555, 2011).
infection (continued). "We used the conditions under which we had observed high viral loads with low variability paired with symptomatic disease: 7-week-old female C57BL/6 mice received 0.1 mg anti-IFNAR1 mAb (ip) followed by infection (ip) with 105TCID50 of CHIKV, MAYV or ONNV 48 h later." (PMID 41532622, 2026). "Therefore, this study aimed to establish a murine infection model using C57BL/6 IFNAR1−/− mice infected with a wild-type YFV strain isolated from a human case during the 2018 outbreak in Brazil, a YFV lineage associated with the country’s largest sylvatic epidemic in decades." (PMID 41157597, 2025). "Regardless of the dose, all Ifnar1-/- and Stat1-/- mice experienced incremental weight loss, increasing clinical signs, and ultimately succumbed to lethal infection between 5–6 dpi and 6–8 dpi, respectively, in sharp contrast to wild-type mice of which 100% survived infection with 103 FFU of USUV." (PMID 40694555, 2025). "Importantly, compared with wild-type (WT) mouse PMs, ARCN1 expression in IFN-I receptor–deficient (IFNAR1 − /−) mouse PMs was not significantly upregulated following RSV-L19 infection." (PMID 41343552, 2025). "However, unexpectedly, PoRVA infection promoted PEDV replication in IFNAR1-deficient (IFNAR1-/-) IPEC-J2 cells, and the RVA-HNNY strain promoted PEDV replication more strongly than the RVA-SXXA strain in both IFNAR1-/- cells and wild-type (WT) cells." (PMID 38905309, 2024). "In addition to IFNAR1, we have also shown the importance of IRF9, a component of the IFN-I-induced signalling complex interferon-stimulated gene factor 3 (ISGF3), in functional T cell responses in LCMV-Arm-infection, with both IFNAR1 and IRF9 independently required in a CD8+ T cell-extrinsic manner." (PMID 38543756, 2024). "To determine if we could experimentally overcome this deficient RRV-specific CD8+ T-cell response, we treated animals in the foot with an anti-IFNAR1 monoclonal antibody (mAb) or used Xcr1-Cre Ifnar1fl/fl mice to modulate the infection of antigen-presenting cells in the DLN." (PMID 39535221, 2024). "Given the different functions of type I IFN vs IFN-λ in HMPV infection, we next tested whether this correlated to differences in lung innate immune cell recruitment by flow cytometry of lung cells in mock- vs HMPV-infected WT, Ifnar1−/−, and Ifnlr1−/− mice early post-infection." (PMID 38530032, 2024). "Finally, IFNAR1−/− mice which are defective innate immune responses were used in this study because immunocompetent mice are not susceptible to MeV37 or MuV38 infection." (PMID 38961063, 2024). "Interestingly, it has been shown that BALB/c IFN-I receptor gene-deficient (Ifnar1-/-) mice are resistant to PR8 infection like BALB/c WT animals, while B6 Ifnar1-/- mice are more susceptible than respective WT controls, due to severe neutrophilic inflammation." (PMID 37771584, 2023). "Furthermore, infection and vaccination with mutant R. parkeri strains showed that Ifnar1 −/−; Ifngr1 −/− double knockout mice may be a good tool for the study of rickettsial pathogenesis, and as models to evaluate vaccine candidates." (PMID 36556330, 2022). "This, together with the liver being a main target organ of L. monocytogenes infection, prompted us to investigate whether and how infection of wt, Irf9-/- or Ifnar1-/- mice changed hepatocyte transcriptomes and, particularly, genes related to metabolic pathways." (PMID 34237114, 2021). "While WT mice showed no clinical signs of infection, including no weight loss whatsoever compared to pre-infection, Ifnar1-/- mice showed appreciable weight loss through the first few days of infection, with weight loss peaking at 10–15%, followed by a gradual return to health." (PMID 33684179, 2021). "Thus, the lack of type I IFN signaling prevented PbAAma1OVA - infection-induced ECM in the genetically deficient Ifnar1-/- mice." (PMID 34659202, 2021).